MPO (myeloperoxidase)
Diseases named in the same sentence as MPO in open-access papers (continued):
Sharing a sentence is not in itself a finding about the gene and the disease.
vasculitis (continued). "However, despite these developments highlighting the role of complement components within leukocytes, our data show that activation of C5 from other sources is important in anti‐MPO vasculitis." (PMID 27235854, 2016). "This type of vasculitis may be myeloperoxidase (MPO) and proteinase 3 (PR3) positive, and its main manifestations are typical cutaneous findings, arthralgia, otolaryngologic involvement, and agranulocytosis." (PMID 27824551, 2016). "Because previous work had shown that the AP was important in anti‐MPO vasculitis, we wondered if properdin was essential and perhaps could initiate complement activation." (PMID 27235854, 2016). "Finally, in view of the recently discovered importance of intracellular complement components 16, 17, 18, 19, 20, 21, we examined the relative importance of bone marrow‐derived and circulating C5 in anti‐MPO vasculitis." (PMID 27235854, 2016). "To assess whether EAV rats developed renal scarring (as is observed in patients with MPO-ANCA vasculitis) we stained renal tissue with periodic acid Schiff (PAS)-silver and picrosirius red." (PMID 27905491, 2016). "Recent data suggest distinct pathogenic pathways for myeloperoxidase (MPO) and proteinase 3 (PR3) ANCA vasculitis, which could result in different modes of presentation and outcome, although overlapping features are not infrequent." (PMID 26123651, 2015). "The link with ANCA vasculitis was made only 6 months later when the patient had developed severe systemic disease in the form of anorexia, wasting, anemia, and an inflammatory syndrome in the context of high MPO-ANCA titers." (PMID 26266064, 2015). "However, individuals with anti-PR3 ANCA vasculitis had significantly higher GI compared with those with anti-MPO disease (p = 0.017)." (PMID 26387933, 2015). "The recently suggested distinct pathogenic pathways for myeloperoxidase (MPO) and proteinase 3 (PR3) anti-neutrophilic cytoplasmic antibodies (ANCA) associated vasculitis could result in different modes of presentation and outcome." (PMID 26123651, 2015). "These diseases are characterized by the presence of ANCA which vary depending on the vasculitis type and whether they are directed against myeloperoxidase (MPO) or proteinase 3 (PR3)." (PMID 26236499, 2015). "However, this glutinous DNA web, which contains a number of antimicrobial peptides including MPO and PR3, can also stick to and damage the endothelium of small blood vessels, causing vasculitis." (PMID 25056155, 2014). "Two reports of newborns who have developed glomerulonephritis and lung haemorrhage within days of delivery to mothers with circulating anti-MPO antibodies and active vasculitis, and responded rapidly to treatment with plasma exchange, provide direct evidence of ANCA-related pathogenicity in humans." (PMID 25056155, 2014). "This may contribute to self-immunization to myeloperoxidase or other neutrophil-associated proteins and the generation of ANCA with subsequent vasculitis." (PMID 25279305, 2014). "The racial difference may affect the selection of PR3-ANCA and MPO-ANCA in the incident of vasculitis." (PMID 24198834, 2013). "However, the level of variable region glycosylation of affinity-purified MPO-ANCA correlated with Birmingham Vasculitis Activity Score (BVAS) (r = 0.641, P = 0.046)." (PMID 22404873, 2012). "A diagnosis of CSS was made on the basis of bronchial asthma, neuropathy of the peroneal nerve and ulnar nerve, findings of angiitis by biopsy of the left sural nerve, increased eosinophil counts, and positivity for myeloperoxidase anti-neutrophil cytoplasmic antibody (MPO-ANCA)." (PMID 22989316, 2012). "Extensive systemic evaluation, including autoimmune and vasculitis testing with antinuclear antibody, extractable nuclear antigen panel, complement levels, and antineutrophil cytoplasmic antibody testing with proteinase-3 and myeloperoxidase antibodies, was repeatedly unremarkable." (PMID 41930087, 2026).
vasculitis (continued). "Notably, pharmaceutical inhibition of cathepsin C has also been shown to suppress NE and PR3 activity in models of vasculitis, resulting in reduced NET burden and decreased disease severity in MPO-ANCA-associated vasculitis (MPO-AAV), a neutrophil-driven autoimmune disorder." (PMID 41303697, 2025). "Anti-neutrophil cytoplasmic antibody (ANCA)-associated vasculitis is group of autoimmune diseases that affect small and medium-sized blood vessels and are characterized by the production of ANCA directed against proteinase 3 (PR3-ANCA) or myeloperoxidase (MPO-ANCA) by B cells." (PMID 39742256, 2024). "Therefore, it seems likely that neutrophils are required in anti‐MPO vasculitis." (PMID 35818684, 2023). "Therefore, this remained a good model of anti‐MPO vasculitis." (PMID 35818684, 2023). "Antineutrophil cytoplasmic antibody (ANCA) associated vasculitis is a multisystemic disease process often resulting in necrotizing arteritis, with immune complex deposits observed in small to medium-sized vessels, including ANCAs directed against proteinase 3 (PR3) and myeloperoxidase (MPO)." (PMID 35538584, 2022). "Alternative dosing strategies with longer dosing intervals and dosing according to peripheral blood CD19 B cell return and PR3/MPO-ANCA rise may be reasonable, temporarily, in stable vasculitis patients with low relapse risk and experienced clinician oversight, to help optimise vaccine responses." (PMID 35641961, 2022). "Recent work has shown that MPO-ANCA may cause NETosis in patients with vasculitis due to its affinity rather than the antibody levels." (PMID 35409152, 2022). "Also, the case of a 45-year-old man with MPO ANCA positive vasculitis after atorvastatin." (PMID 36419545, 2022). "Overall, although many obstacles still need to be overcome before tolerogenic cell therapy becomes a reality for vasculitis patients, autologous Tregs and ex vivo-derived MPO-loaded tolerogenic DCs offer promise to be a feasible and successful antigen-specific treatment for MPO-AAV." (PMID 34394071, 2021). "Moreover, a transient positivity of anti-neutrophil cytoplasmic antibodies (ANCA), with anti-proteinase 3 or anti-myeloperoxidase specificity, has been reported in 10% of patients during acute PVB19 infection, and is a potential pitfall for the diagnosis of ANCA-associated vasculitis." (PMID 32646497, 2020). "Currently, there is only one in vivo model for MPO-ANCA vasculitis, but not for the associated PR3." (PMID 26236499, 2015). "This was particularly evident in 56% of the patients with MPO/pANCA vasculitis, and similarly, 41% of those with PR3/cANCA vasculitis demonstrated comparable outcomes." (PMID 39797292, 2025). "MPO-ANCA-positive vasculitis mainly affects lungs and kidneys, less frequently eyes, ear, nose, and throat, while PR3-ANCA-positive vasculitis is characterized by predominant involvement of the upper respiratory tract." (PMID 40870415, 2025). "This patient also showed lower levels of MPO-ANCA, Birmingham Vasculitis Activity Score (BVAS), and C-reactive protein." (PMID 38873394, 2024). "Kidney involvement was noted in a majority of participants with MPO-ANCA (88%, 111/126) and PR3-ANCA (77%, 179/232), as well as half of the individuals with ANCA-negative vasculitis (50%, 20/40)." (PMID 38886004, 2024). "Our findings invite reconsideration of roles for autoantigens other than MPO and PR3 in pediatric vasculitis, particularly in medium- and large-sized blood vessels." (PMID 38612581, 2024). "Both MPO-ANCA and PR3-ANCA seropositive cases also exhibited higher frequencies of kidney involvement than ANCA-negative vasculitis." (PMID 38886004, 2024). "A retrospective analysis of 101 patients with MPO-positive and 54 PR3-positive vasculitis was performed, using laboratory established cut-off value, measured by chemiluminescence." (PMID 37676628, 2024).
vasculitis (continued). "In our study, 92.3% of patients presented MPO-ANCA positivity, and the development of ILD preceded that of vasculitis in 66.7% of patients." (PMID 36794274, 2023). "The majority of studies looking into the role of fatigue in vasculitis have focused on disease subtype, and though some have investigated fatigue in AAV, few have compared differences between the PR3-ANCA and MPO-ANCA serotypes." (PMID 36890852, 2023). "MPO inhibitors, PF-1355 and AZM198, have been shown to attenuate neutrophil degranulation and NET formation by inhibiting MPO activity in vasculitis." (PMID 36902466, 2023). "Although we were unable to gather histological evidence of vasculitis, she was diagnosed with EGPA by a rheumatologist based on adult-onset eosinophilic airway inflammation, nasal polyps, neuropathy, MPO-ANCA positivity, eosinophilia and clinical history." (PMID 37076824, 2023). "We argue that following G-CSF treatment, MPO antibodies were formed leading to signs and symptoms of ANCA vasculitis correlating to a Birmingham vasculitis activity score (BVAS) of 18 ‘new’ points." (PMID 36000895, 2022). "Another case of a 54-year-old man with ANCA-positive vasculitis, positive for ANA and anti-MPO after simvastatin/ezetimibe." (PMID 36419545, 2022). "The patients with positive MPO-ANCA had higher disease activity and rates of renal involvement, biopsy-proven vasculitis, fever, and myalgia." (PMID 35833130, 2022). "According to our cohort, the MPO-ANCA–positive group had more severe inflammation, higher disease activity and frequencies of renal involvement and biopsy-proven vasculitis, and the ANCA-negative group developed more cardiac manifestations and asthma." (PMID 35833130, 2022). "Patients with positive MPO-ANCA had higher levels of erythrocyte sedimentation rate (ESR), C-reactive protein, Birmingham Vasculitis Activity Score (BVAS), higher ratios of fever, myalgia, renal involvement, and biopsy-proven vasculitis." (PMID 35833130, 2022). "Compared with the ANCA-negative group, the MPO-ANCA–positive group had higher CRP and percentage of vasculitis suggested by sural nerve biopsy but lower eosinophil infiltration in affected tissues." (PMID 35833130, 2022). "As we aimed to examine the development of AS during MPO-AAV treatment, we excluded the patients who had AS at the onset of vasculitis." (PMID 33481903, 2021). "As has been described for vasculitis, predominantly intracellular autoantigens such as PR3 and MPO are transiently expressed on the cell surface, and thereby they become accessible to autoantibody binding and are directly involved in disease pathogenesis." (PMID 33763057, 2021). "In patients with vasculitis activated neutrophils, PR3 and MPO proteins traffic to the plasma membrane surface, making these normally intracellular primary granule enzymes accessible to autoantibody binding." (PMID 33763057, 2021). "Subsequent adoptive transfer/antibody blockade experiments showed that MPO/BAY DC-induced Tregs suppressed anti-MPO immunity and vasculitis via IL-10." (PMID 34394071, 2021). "In this study, we confirm the distinct clinical phenotypes of MPO-ANCA(+) and PR3-ANCA(+) disease; we describe differences in histology, but, in addition, we point out the similarities between MPO-ANCA(+) and ANCA(-) vasculitis." (PMID 35127750, 2021). "Chronic T cells activation promotes B cells secretion of antineutrophil cytoplasmic antibodies (ANCAs) targeting proteinase 3 (PR3) or myeloperoxidase (MPO) which trigger neutrophil activation and lead to vasculitis." (PMID 33287743, 2020). "The continuous production of PR3-ANCA and MPO-ANCA from lymphocytes results in a vicious cycle of neutrophil hyperactivation, inflammatory activity, and vasculitis." (PMID 33023023, 2020). "Vasculitis specific commercial automated ALBIAs can measure multiple antibodies of interest from the same serum sample in a single tube including PR3-ANCA, MPO-ANCA, and anti-glomerular basement membrane (anti-GBM) antibody." (PMID 33013868, 2020).
vasculitis (continued). "Several of the molecules decorating the NETs (e.g., MPO, ds-DNA, histones, etc.)are autoantigens in systemic autoimmune diseases such as antineutrophil cytoplasmic antigen (ANCA)-positive vasculitis and systemic lupus erythematosus (SLE)." (PMID 32850525, 2020). "In an active model of disease, MPO-ANCA and features of vasculitis developed in rats given PTU in addition to intraperitoneal PMA, with evidence of DNase1-resistant abnormal NET formation." (PMID 32373109, 2020). "“Double positive” vasculitis, with anti-glomerular basement membrane (GBM) and anti-MPO seropositivity, has been previously reported in a case of PTU-associated pulmonary-renal syndrome, with histological evidence of anti-GBM disease." (PMID 32703233, 2020). "GO enrichment analysis identified a crucial role of the IFN-γ mediated signaling pathway and showed comparable involvement in both, MPO-ANCA and PR3-ANCA vasculitis." (PMID 30795559, 2019). "For instance, although GPA and PR3-ANCA vasculitis are more common in Western countries, MPA and MPO-ANCA vasculitis are more frequent in Asian countries." (PMID 31694209, 2019). "In contrast, in patients with MPO-ANCA nephritis with a UIP pattern, deaths were more frequently related to anti-immune therapy (infectious complication) or vasculitis itself (alveolar hemorrhage and perhaps cardiovascular disease)." (PMID 31675941, 2019). "Around a third of EGPA patients develop ANCA against MPO and clinical features that overlap with MPO+ AAV, such as vasculitis and necrotising glomerulonephritis." (PMID 31719529, 2019). "There are many ANCA specificities in different autoimmune diseases but only myeloperoxidase (MPO) and proteinase 3 (PR3) that are expressed on the surface of primed neutrophils are major ANCA-antigens in vasculitis." (PMID 31616410, 2019). "Evidence for involvement of the complement system in AAV comes from murine models of MPO-ANCA-induced glomerulonephritis and vasculitis, demonstrating activation of the alternative complement pathway and specifically C5 being essential for disease induction." (PMID 29686675, 2018). "Therefore, we could not examine the effect of PAD inhibitors on MPO-ANCA-associated vasculitis in this model, which is another limitation of this study." (PMID 27375623, 2016). "Lymphoma may be associated with ANCA positivity for both PR3 and MPO without vasculitis." (PMID 27293945, 2016). "Patients with vasculitis associated with levamisole-adulterated cocaine classically demonstrate unique serologic abnormalities characterized by unusually high titers of p-ANCA without substantial antibodies against myeloperoxidase (MPO), the typical target of p-ANCA." (PMID 25943359, 2015). "ANCAs-IgG were prepared from 4 patients with active MPO-ANCA-positive vasculitis and 2 patients with active PR3-ANCA-positive vasculitis, respectively." (PMID 23785491, 2013). "The high levels of PR3-ANCA and MPO-ANCA, which is thought to be a specific marker of anti-thyroid drug-induced vasculitis, decreased in correlation with the course of symptoms and the resolution of radiologic findings after PTU withdrawal." (PMID 22958435, 2012). "ANCAs-postive IgG were prepared from 5 patients with active MPO-ANCA-positive vasculitis and 3 patients with active PR3-ANCA-positive vasculitis, respectively." (PMID 22675451, 2012). "In another study, ANCA were evaluated by IIFT and ELISA for anti-PR3 and anti-MPO antibodies and ANCA were found in three out of 29 patients (10%), mainly those with vasculitis." (PMID 23674967, 2006). "Notably, the patient had dual positivity for MPO-ANCA and PR3-ANCA, a rare finding that raised suspicion of drug-induced vasculitis, consistent with findings from prior retrospective studies." (PMID 39906456, 2025). "Its potential benefit may derive from rapid removal of circulating MPO-ANCA, immune complexes, and pro-inflammatory mediators, thereby reducing ongoing endothelial injury in severe vasculitis presentations." (PMID 41357727, 2025).
vasculitis (continued). "To elaborate, patients with renal-limited disease or patients with any form of vasculitis but without any proof of granulomas are more likely to have MPO-ANCA." (PMID 40430184, 2025). "While renal biopsy is definitive, it is not essential in typical presentations with positive MPO- or PR3-ANCA with low suspicion for secondary vasculitis or mimics." (PMID 39927255, 2025). "Serologies to assess for vasculitis included negative anti-myeloperoxidase (MPO), anti-proteinase 3 (PR3), anti-glomerular basement membrane (GBM), and antistreptolysin antibodies." (PMID 39726463, 2024). "The 5 test items for vasculitis suggested positive P-ANCA and MPO-Ab." (PMID 39312300, 2024). "Secondly, in previous guidelines for diagnosing IPF, ANCA testing was included only when vasculitis was suspected, but MPO-ANCA ILD tend to present without common signs of vasculitis." (PMID 38445024, 2024). "A specific linear epitope on MPO was identified that is targeted by autoantibodies in ANCA-negative patients and often masked by serum proteins, providing a new understanding of the ANCA-negative subset of vasculitis." (PMID 39456878, 2024). "Furthermore, ANCA vasculitis can be classified into proteinase 3 (PR3-ANCA) and myeloperoxidase (MPO-ANCA) which are cytoplasmic antigens that are present at the surface of cytokine-stimulated leucocytes." (PMID 39310478, 2024). "Anti-neutrophil cytoplasmic antibody (ANCA)-associated vasculitis (AAV) is a heterogeneous group of small vasculitis of unknown etiology, characterized by the presence of proteinase 3 (PR3) and myeloperoxidase (MPO) in the serum." (PMID 39726748, 2024). "In contrast to another model of anti-MPO vasculitis, the model is not autoimmune as it relies on passive transfer of antibody." (PMID 36154801, 2023). "Anti‐MPO vasculitis was induced with sheep anti‐MPO IgG to induce more severe disease, because we had not shown protection from acute kidney injury in our initial experiment." (PMID 35818684, 2023). "First, this previous work in an autoimmune model of MPO vasculitis showed that mast cells enhanced autoimmunity, which is not a feature of the model we used." (PMID 36154801, 2023). "A systematic review and analysis of GWAS studies revealed 20 SNPs associated with MPO-ANCA and 134 with PR3-ANCA vasculitis, with no overlapping SNPs." (PMID 37239388, 2023). "This system includes clinical (peripheral nerve disorder, asthma, lung, and skin involvement), laboratory (RF positivity, MPO-ANCA positivity, IgE, and CRP elevation), and histological features (vasculitis detected by pathological examination), which have been awarded a point weight." (PMID 37215720, 2023). "Vasculitis subtype had no bearing on fatigue, but the MPO-ANCA serotype displayed appreciably higher rates of fatigue." (PMID 36890852, 2023). "Infectious complications have been shown to trigger MPO-ANCA and vasculitis that might impact outcome and survival." (PMID 36430804, 2022). "Interestingly, the same study reported genetic variations in the Enho gene after analyzing myeloperoxidase (MPO) and anti-neutrophil cytoplasm autoantibody (ANCA) in patients with vasculitis and healthy individuals." (PMID 35955453, 2022). "Therefore, AAV is also classified into MPO-ANCA vasculitis, PR3-ANCA vasculitis, and ANCA-negative vasculitis based on the presence of ANCA types." (PMID 35655922, 2022). "The biopsy-proven vasculitis (44.4% vs. 8.7%, p = 0.04) and fever (85.0% vs. 42.4%, p = 0.002) in patients with MPO-ANCA were more common than in patients without ANCA." (PMID 35833130, 2022). "Only 10.0% of patients were ANCA positive on IIF, mostly as atypical xANCA (titer 1:80–1:320), with none of them showing reactivity to vasculitis specific PR3 or MPO antigens." (PMID 36106319, 2022).